CST1 (cystatin SN)
Diseases named in the same sentence as CST1 in open-access papers (continued):
Sharing a sentence is not in itself a finding about the gene and the disease.
cyst (continued). "The transcription levels of cst1 in the bag1 knockout strain were consistently lower than in the parental strain, both in early in vitro induction and in mouse brain cysts, indicating a compromised cyst-forming ability." (PMID 39080770, 2024). "All antibodies showed their expected localization patterns: GAP45 outlined the parasite shape; GRA2 was split between intracellular punctate staining, presumably within dense granules, and the periphery of the cyst; and CST1 localized around the cyst periphery." (PMID 39189782, 2024). "CST1, a large glycoprotein with a mucin-like structural domain, is present at multiple stages of the T. gondii life cycle and is essential for constructing a complete cyst wall and providing structural rigidity." (PMID 39599575, 2024). "The mucin domain of CST1 is highly O-GalNAc glycosylated and modified by the enzymes called polypeptide N-acetylgalactosaminyltransferases (ppGalNAc-Ts), which are required for the formation of a mechanically stress-resistant cyst wall." (PMID 36439853, 2022). "Notably, a similar phenotype was reported for GRA12 depleted parasites, which display an apparently intact IVN but exhibit a delay in the accumulation of the CST1 major cyst wall protein at the cyst periphery." (PMID 35573773, 2022). "Finally, we examined the effect of CB-839 on T. gondii cyst wall CST1 formation in iPSC-derived glutamatergic neurons." (PMID 35096641, 2021). "Deletion of the cyst wall protein (CST1) changes the landscape of the cyst wall and as a result compromises cyst wall stability, which disrupts cyst maintenance and is evidence that the cyst wall is a prominent cyst structure that maintains parasite viability during chronic infection." (PMID 33883265, 2021). "Finally, NAC strongly decreased formation of the characteristic CST1-rich cyst wall by T. gondii in myotubes (p < 0.001; ANOVA) as indicated by labelling with the Dolichos biflorus lectin at 72 hours after infection." (PMID 34881198, 2021). "We found that CB-839 treatment inhibited IFN-γ-induced cyst wall CST1 formation." (PMID 35096641, 2021). "In addition, s-WGA colocalized in the cyst wall with CST1, suggesting that N-acetylglucosamine- and N-acetylgalactosamine-decorated molecules colocalized in the cyst wall." (PMID 32132158, 2020). "N-Acetylgalactosamine-modified CST1 has been hypothesized to be a key cyst wall scaffolding molecule that interacts with other cyst wall proteins to provide a walled structure that supports cyst stability." (PMID 32132158, 2020). "While CST1 has been found to be important for maintaining cyst wall integrity and establishment of chronic infection, ΔCST1 parasites still retain the ability to create cysts composed of a thin cyst wall." (PMID 32075884, 2020). "We also detected differential phosphorylation of the cyst wall proteins CST1, CST3, CST4, and CST6." (PMID 32907954, 2020). "Next, the localization of cyst wall proteins CST1, MAG1, and MCP4 as well as the α-N-acetylgalactosamine sugar pattern on the cyst wall (as detected by fluorescein-conjugated Dolichos biflorus agglutinin lectin) of these cyst wall protein knockouts was assessed by IFA." (PMID 32019789, 2020). "The glycosylated mucin domain of CST1 could provide extensive carbohydrate bonding interactions with other cyst wall-localized proteins." (PMID 31619500, 2019). "CST1 possesses a mucin domain that is essential for the granular appearance of the cyst wall." (PMID 31619500, 2019). "CST1 is hypothesized to bind to the cyst matrix face of the limiting cyst membrane and act as a scaffolding protein for the construction of the cyst wall." (PMID 31619500, 2019). "Deficiency of pp-GalNAcT2 or T3 leads to fragile brain cysts, likely due to the absence of CST1 glycosylation, while a lower cyst load in the brain was observed in TgNST1-deficient parasites." (PMID 30773146, 2019).
cyst (continued). "GRA1, GRA4, GRA6, GRA9, and GRA12 on day 1 and day 2, and GRA2 on day 2, exhibited cyst periphery/cyst interior ratios that were greater than the ratio for the cyst wall protein CST1, indicating that these GRA proteins were components of the developing wall early during cyst development." (PMID 31619500, 2019). "A previously proposed model for how the cyst wall could develop is based on a CST1 protein scaffold." (PMID 31619500, 2019). "Despite the pepsin treatment, some known cyst wall markers, such as CST1 and GRA2, were seen." (PMID 31726967, 2019). "All of the mutants, when cultured under bradyzoite induction conditions, displayed a CST1-positive cyst wall, demonstrating that all of the mutants could undergo bradyzoite differentiation in response to bradyzoite culture conditions." (PMID 28851850, 2017). "SRS44 is also known as CST1 and is a key component of the tissue cyst wall." (PMID 28362800, 2017). "To assess the role of ASP5 in cyst wall formation, we used the fluorescent Dolichos biflorus Agglutinin (DBA) lectin to detect the glycosylated protein CST1 (one of the few available markers of the T. gondii cyst wall), following pH induced differentiation of PRUΔku80Δasp5 strain parasites in vitro." (PMID 26473595, 2015). "Therefore, CST1 was selected as a biomarker for identifying chronic T. gondii infection due to its critical role in the cyst wall, its ability to induce strong humoral immune responses, its specificity and immunogenicity, and its potential application in serological testing." (PMID 39599575, 2024). "Furthermore, we examined the effect of CB-839 on T. gondii cyst wall CST1 formation." (PMID 35096641, 2021). "Thus, while s-WGA colocalized with GRA4, GRA6, and CST1, which traffic to the cyst wall via a GRA2-dependent pathway, the N-acetylglucosamine-modified molecule(s) that binds s-WGA traffics to and accumulates at the cyst wall through GRA2-independent mechanisms." (PMID 32132158, 2020). "Therefore, we took advantage of Percoll density-based fractionation of fragmented infected host cells followed by immune separation of the cyst wall-containing fraction with a CST1-specific monoclonal antibody to enrich for cyst wall-containing samples and to reduce parasite body contamination." (PMID 31040239, 2019). "In accordance with these hypotheses, genetic deletion of the BPK1 gene affected the transmission of the parasite through the GI tract, and genetic deletion of the CST1 gene reduced cyst sturdiness and cyst number in the brains of mice with persistent infection." (PMID 31040239, 2019). "Our finding that PruΔgra12 cysts exhibited a reduced intensity of DBA fluorescence at the cyst periphery compared to the intensity at the cyst interior suggested that GRA12 could regulate delivery or retention of the major cyst wall protein CST1 during the development of the cyst wall." (PMID 31266861, 2019). "Several GRAs, including GRA55, CST1, GRA76, and GRA50, are essential for cyst formation and maintenance." (PMID 40941387, 2025). "We used this method to assess the co-localization of CST1 and GRA2 in the cyst wall and observed distinct localization of GRA2 at this higher resolution." (PMID 39189782, 2024). "While previous data have shown a smooth overlapping signal for CST1 and GRA2 in the in vitro cyst wall, we observe a more punctate distribution of GRA2 in the cyst wall compared to the smooth signal of CST1 with StcE-enhanced U-ExM." (PMID 39189782, 2024). "For instance, CST1/SRS44, a mucin-like domain glycoprotein, is essential to construct and maintain an intact and rigid cyst wall." (PMID 34262559, 2021). "The major cyst wall glycoprotein CST1, at least 22 dense granule (GRA) proteins, and other proteins, including CST4, BPK1, MAG1, MCP3, MCP4, and MYR1, were identified in the cyst wall/membrane of in vitro cysts." (PMID 32132158, 2020).
cyst (continued). "Similar to what has been seen with CST1 and MAG1, we found that CST7, -8, -9, and -10 also display some degree of tachyzoite parasitophorous vacuole matrix localization but localize to the cyst wall and matrix in the bradyzoite stage." (PMID 32019789, 2020). "In addition, CST1 has been shown to be important for the robustness of cysts with respect to withstanding physical, mechanical stress, for the maintenance of bradyzoite gene expression, and for the formation of the cyst wall as observed with transmission electron microscopy (TEM)." (PMID 32075884, 2020). "The deletion of GRA2 did not affect the trafficking or cyst wall accumulation of the molecules that bind s-WGA in the cyst wall, and the cyst wall molecule(s) that binds s-WGA was colocalized with GRA4, GRA6, and CST1." (PMID 32132158, 2020). "We quantitatively measured CST1 and s-WGA fluorescence intensities at the cyst periphery compared to those at the cyst interior." (PMID 32132158, 2020). "The genetic deletion of GRA2 disrupted the organization of the cyst matrix, altered the staining patterns of GRA4 and GRA6 in the cyst matrix, and delayed the accumulation of GRA4, GRA6, and DBA-stained CST1 in the cyst wall." (PMID 32132158, 2020). "Analysis of the cyst wall interactome model revealed that CST1, MAG1, and MAG2 have the highest in-degrees between all proteins, signifying that they were the most common proteins identified from all cyst wall BirA* pulldowns." (PMID 32019789, 2020). "Within the interactome model, it can be appreciated that CST1, MAG1, and MCP4 are the central components of each cyst wall pulldown." (PMID 32019789, 2020). "Additional studies are necessary to identify the structures formed by colocalized CST1- and s-WGA-binding molecules in the cyst wall." (PMID 32132158, 2020). "By comparing the ratio of the signal intensity from CST1 versus ALD1 in each fraction, the middle interlayer was found to contain the highest ratio of cyst wall fragment proteins compared to parasite body/cytosolic protein contamination." (PMID 31040239, 2019). "The CST1 mucin domain is heavily glycosylated, and this explains why DBA selectively stains CST1 and the cyst wall." (PMID 31619500, 2019). "Remarkably, deletion of the AP2IV-4 locus resulted in the expression of a subset of bradyzoite-specific proteins in replicating tachyzoites that included tissue cyst wall components BPK1, MCP4, CST1 and the surface antigen SRS9." (PMID 29718996, 2018). "One of the early chronic-stage markers, CST1, is the major structural element of the cyst wall, and parasites lacking cst1 form fragile cysts." (PMID 39189782, 2024). "GRA2 appears to have a dynamic cyst-wall localization being present in early cysts at day 7 (D7) and D10, with its location overlapping with the CST1 signal, while being absent from the wall in late cysts." (PMID 39189782, 2024). "CST1 exhibits N-acetylgalactosamine moieties that are recognized by Dolichos biflorus agglutinin (DBA) as well as succinylated wheat germ agglutinin (s-WGA), which promotes staining of the cyst wall." (PMID 36566237, 2022). "The DBA stain was measured at the cyst periphery, which reflects CST1 molecules at the cyst wall compared to the cyst interior, which reflects CST1 molecules not yet at the cyst wall." (PMID 33883265, 2021). "Together, N-acetylgalactosamine-modified CST1- and N-acetylglucosamine-modified s-WGA-interacting molecules may coordinate the scaffolding and building of the cyst wall." (PMID 32132158, 2020). "This band likely corresponds to the increased biotinylated signal observed at the cyst wall without exogenous biotin (CST1-BirA* panel)." (PMID 32019789, 2020). "We did not observe any gross change is cyst size or morphology, and did not observe fragility of the cysts while manipulating the samples for counting as has been seen in the CST1 deletion mutants." (PMID 32374791, 2020).
cyst (continued). "When exogenous 150 μM biotin was supplemented to the bradyzoite-inducing medium, the BirA* tag fused to MAG1, MCP4, BPK1, CST1, and GRA6 displayed biotinylation activity as an increase in streptavidin signal that was observed at the cyst wall compared to that in the Pru strain under IFA." (PMID 32019789, 2020). "DBA fluorescence intensity was quantitatively measured at the cyst periphery, which reflects CST1 cargo delivered to the cyst periphery, and was compared to that in the cyst interior, which reflects CST1 cargo not yet delivered to the cyst wall/membrane." (PMID 31941814, 2020). "Colocalization of the HA signal from each transgene was observed at the cyst wall with CST1 serving as the cyst wall marker, demonstrating that the BirA* tag did not disrupt cyst wall localization of these proteins." (PMID 32019789, 2020). "In addition, CST1, GRA2, GRA5, GRA6, GRA7, and GRA12 occupy both cyst wall layers, while GRA1, GRA4, and GRA9 occupy only the inner layer of the cyst wall in mature in vitro cysts." (PMID 32132158, 2020). "Colocalization of CST1 and s-WGA was detected at the cyst periphery." (PMID 32132158, 2020). "GRA1, found at one of the highest levels in EVs, at this early time point of cyst development is found on the outer layer of the cyst, and is not pulled down in the presence of CST1 (carbohydrate components of the tissue cyst) and is dispensable for cyst growth and stability." (PMID 40523037, 2025). "Green fluorescent protein-positive (GFP+) bradyzoites and cyst wall proteins stained by DBA were visible within the developing cyst 6 h after differentiation, showing that alkaline switch differentiation rapidly upregulated expression of bradyzoite-stage genes such as LDH2 and CST1." (PMID 31941814, 2020). "In comparison to the parental PruΔku80 strain that expressed GRA12, PruΔgra12 cysts exhibited a significant decrease in the DBA fluorescence intensity ratio (cyst periphery/cyst interior), suggesting that GRA12 could be involved in the delivery of CST1 to the cyst wall." (PMID 31266861, 2019). "CST1, which is found in the cyst wall of T. gondii, contains a mucin-like domain, and we have previously demonstrated that this domain is essential for cyst stability and that the absence of this domain alters the ultrastructure of the cyst wall." (PMID 28074022, 2017). "Cysts from the D7 bradyzoite culture labeled with antibodies against CST1 and GRA2 demonstrate the expected protein localizations after 4-h incubation with StcE at 37°C, showing that it does not destroy the cyst wall or disrupt antibody binding." (PMID 39189782, 2024). "In contrast to CST1, GRA4, and GRA6, the relative accumulation of the molecules that bind s-WGA in the cyst wall was not dependent on the expression of GRA2." (PMID 32132158, 2020). "In agreement with in vitro cysts not containing the full complement of proteins present in in vivo cysts, neither this study nor the CST1 pulldown identified BCP1, which has only been identified in the cyst wall of in vivo derived cysts." (PMID 32374791, 2020). "Top hits detected from the WT sample, but not from the CST1-KO sample, contained several known cyst wall proteins, including CST1, BPK1, MAG1, MCP4, GRA2, GRA3, and GRA5, which validate this proteomic approach for identifying cyst wall components." (PMID 31040239, 2019). "However, unlike CST1/SRS44, SRS13 is not necessary for the assembly of the cyst wall." (PMID 34262559, 2021).
gastric cancer (25 papers, 2013 to 2025). A primary or metastatic malignant neoplasm involving the stomach. "CST1 was well-known as a cysteine protease inhibitor that protects against allergen and viral, and was associated with the gastric cancer process." (PMID 39721372, 2025). "Numerous studies have implicated CST1 in the progression of various tumors, including gastric cancer, colorectal cancer, and breast cancer." (PMID 40535419, 2025). "Univariate and multivariate Cox regression model analysis revealed that high expression of CST1 was an independent risk factor for the prognosis of gastric cancer patients." (PMID 36369321, 2023). "Several studies demonstrated that CST1 was closely associated with cell proliferation and metastasis in various cancers, including cancer of the stomach, breast, colorectum, pancreas, and bile duct." (PMID 33968941, 2021). "The mRNA level of CST1 is increased in gastric cancer tissues and is closely linked to the pTNM stage." (PMID 29383149, 2017). "Aberrant CST1 expression has been reported to be associated with the occurrence, proliferation, invasion, and recurrence of several malignancies, including breast, pancrea, lung, hepatocellular carcinomas and gastric cancer." (PMID 36848349, 2023). "Besides, elevation of CST1 is a promising diagnostic biomarker for other cancer types, including pancreatic cancer, esophageal squamous cell carcinoma, and gastric cancer." (PMID 33968941, 2021). "In gastric cancer, both CST1 and OTUB1 are involved in the development and progression of the disease." (PMID 40387552, 2025). "The results in this study mainly investigate the molecular mechanisms of CST1 promoted gastric cancer development by activating AKT pathway." (PMID 39721372, 2025). "Recent research has established a connection between CST1′s influence on the AKT signaling pathway and the advancement of gastric cancer, indicating that CST1 can promote the gastric cancer process by targeting the AKT pathway." (PMID 39721372, 2025). "The results indicated that CST1 regulating the AKT pathway was correlated with gastric cancer progress." (PMID 39721372, 2025). "These outcomes suggested that the activation of AKT pathway can promote the gastric cancer process, and CST1 promoted gastric cancer development via AKT pathway." (PMID 39721372, 2025). "A limitation of the present study was that the authors only conducted an in vitro study to investigate the molecular mechanisms of CST1 regulating AKT pathway in gastric cancer, and further clinical study was needed to manage." (PMID 39721372, 2025). "Clinical cohort studies demonstrate significantly elevated CST1 levels in peripheral blood and ascites of gastric cancer patients with metastasis, with multivariate survival analyses confirming its role as an independent prognostic indicator." (PMID 40919133, 2025). "CST1 inhibits ferroptosis and promotes gastric cancer metastasis by regulating GPX4 protein stability." (PMID 40136465, 2025). "We also found that the expression of CST1 was elevated in specimens of gastric cancer, which is closely related to the degree of differentiation of gastric cancer tissue and lymph node metastasis." (PMID 36369321, 2023). "In this study, we explored the role of cysteine protease inhibitor SN (Cystatin SN, CST1) in promoting gastric cancer metastasis." (PMID 36369321, 2023). "Moreover, clinical data suggested that CST1 is significantly increased in peripheral blood and ascites of gastric cancer patients with metastasis; multivariate Cox regression model analysis showed that CST1 was an independent risk factor for the prognosis of gastric cancer patients." (PMID 36369321, 2023). "Overall, our results elucidated a critical pathway through which high CST1 expression protects gastric cancer cells from undergoing ferroptosis, thus promoting its progression and metastasis." (PMID 36369321, 2023).